HIF1A (hypoxia inducible factor 1 subunit alpha)
Diseases named in the same sentence as HIF1A in open-access papers (continued):
Sharing a sentence is not in itself a finding about the gene and the disease.
thyroid cancer (continued). "The decreased HIF-1α expression was correlated with reduced expression of hypoxia-related glucose transporter 1 (GLUT1) in thyroid cancer cells." (PMID 29084538, 2017). "Our current observations consistently show that SDHD-G12S and SDHD-H50R, as well as SDHD knockdown, lead to functional insufficiency of SDH and increased stability of HIF-1α in thyroid cancer cell lines." (PMID 25149476, 2015). "They showed HIF-1α expression to be elevated in thyroid carcinomas and to correlate with malignancy, making it a potential target for thyroid cancer therapy." (PMID 23824493, 2013). "In contrast, S1P-induced HIF-1α expression in ML-1 thyroid cancer cells is mediated by the pro-migratory S1P3 as well as Gi." (PMID 23824493, 2013). "For instance, it has been demonstrated that lactic acid generated from thyroid cancer cells (including TCSCs) stimulates the production of HIF-1α and activates the macrophage AKT/mTOR signaling pathway, increasing macrophage polarization towards the M2-like TAM." (PMID 39776907, 2024). "Hypoxia is a significant cause of metastasis and recurrence in cervical lymph nodes of PTC, and mechanistic studies reveal that in a hypoxic environment, FGF11 forms a positive feedback loop with HIF1α, which in turn promotes thyroid cancer growth and metastasis." (PMID 38902782, 2024). "There is a lack of research on the relationship between OSAS and thyroid cancer at the present, however, HIF1A is closely associated with both diseases." (PMID 36937508, 2023). "FGF11 interacted with HIF1A to increase thyroid cancer growth and metastasis." (PMID 36937508, 2023). "Moreover, HIF1A expression was highly expressed in thyroid cancer compared with that in normal thyroid." (PMID 36994412, 2023). "We further explored whether KDM1A regulated DKK1 expression through the HIF-1α/microRNA-146a axis in thyroid cancer." (PMID 35198054, 2022). "Interestingly, both HIF1α and β-catenin were found to be overexpressed in more aggressive thyroid cancer types and are redox-regulated in other cell types." (PMID 35682803, 2022). "In our previous research, we demonstrated SIRT6 interacted with HIF-1α in thyroid cancer cells." (PMID 33436551, 2021). "Indeed, VEGF is another well-known target of HIF-1α in thyroid cells and it is known to be increased in HT and in thyroid cancers." (PMID 33916948, 2021). "In summary, although many complicated questions have not been answered, our study was the first to identify the mTOR/HIF1α/ENO1 pathway in thyroid carcinoma progression and ENO1 as a regulator of CST1, thereby paving the way for early diagnosis and efficient therapy of thyroid carcinoma." (PMID 33968941, 2021). "Nevertheless, it is unclear whether the hypoxia-related mTOR/HIF1α pathway participates in thyroid carcinoma progression." (PMID 33968941, 2021). "Like other cancers, HIF-1α is likely to play a pivotal role in the progression of thyroid cancer." (PMID 32847004, 2020). "Thus, evaluation of the effects of HIF-1α inhibition in the mutant BRAF thyroid cancer cell line (BCPAP) would have a significant clinical implication in terms of the high BRAF mutation prevalence in thyroid cancer and its association with poor outcomes." (PMID 32847004, 2020). "In this context, HIF-1α inhibitors, which target post-transcriptional processes, could be an appropriate treatment for thyroid cancer." (PMID 32847004, 2020). "There is an important correlation between PI3K/AKT and HIF-1a, which may have specific connection with disease progression in thyroid cancers." (PMID 32493394, 2020). "However, only limited numbers of studies have evaluated the effects of HIF-1α inhibitors on thyroid cancer progression." (PMID 32847004, 2020). "Interestingly, a link between HIF-1α and BRAF mutations, which are a prevalent and well-known poor prognostic factor in papillary thyroid cancer, was suggested in thyroid cancer." (PMID 32847004, 2020). "This is a study infirmed SIRT6/HIF-1α axis in thyroid cancer for the first time." (PMID 30675128, 2019).
thyroid cancer (continued). "A thorough grasp of the HIF-1α signaling pathway’s mechanism of action and its target genes may aid in developing novel therapeutic approaches that block tumor growth and metastasis and target HIF-1α or its downstream target genes, potentially opening up new treatment options for thyroid cancer." (PMID 40917751, 2025). "We speculated that HIF1α might mediate oncogenic roles of TET1 in thyroid cancer." (PMID 37020036, 2023). "Interestingly, the modulation of Hif-1α expression can affect the sensitivity to radiotherapy in thyroid neoplasia and to chemotherapy in multiple tumours, making it a promising therapeutic target for many cancer types, including thyroid carcinomas." (PMID 37198319, 2023). "Thus, HIF-1α represents a potential therapeutic target for the treatment of thyroid cancer." (PMID 36699028, 2022). "Additionally, HIF-1α silencing has been described to promote thyroid cancer cells apoptosis." (PMID 34539584, 2021). "Therefore, enhanced glycolysis may be the reason why mTOR/HIF1α/ENO1 promotes thyroid carcinoma progression." (PMID 33968941, 2021). "HIF-1α inhibition could be a therapeutic target for thyroid cancers with high HIF-1α expression." (PMID 32847004, 2020). "Thus, HIF-1α could be controlled by post-transcriptional modulation, and drugs that modulate HIF-1α stability at post-transcriptional levels might be effective treatments in thyroid cancer." (PMID 32847004, 2020). "However, few studies have investigated HIF-1α as a target for thyroid cancer treatment." (PMID 32847004, 2020). "However, few studies have investigated the role of HIF-1α inhibition in thyroid cancer progression." (PMID 32847004, 2020). "Accumulating studies have shown that the HIF1α-VEGF pathway is activated in the progression of thyroid cancer, and PEDF could suppress tumor growth by the down-regulation of VEGF expression by inhibiting HIF1α, which showed the anti-angiogenic activity of PEDF." (PMID 27936049, 2016). "In the thyroid cancer cell line FTC133, HIF-1α overexpression increased Twist gene expression, whereas inhibition of HIF-1α activity abrogated the increase in Twist gene expression under hypoxic conditions." (PMID 40530008, 2025). "For instance, HIF-1α can increase GLUT1 and GLUT3 expression, increase the uptake of glucose by thyroid cancer cells, and provide substrates for glycolysis to meet their energy needs through SLC2A1 (encoding GLUT1) and SLC2A3 (encoding GLUT3)." (PMID 40917751, 2025). "This research examines the relationship between HIF1A, TNM, and thyroid cancer stage to determine the impact of HIF1A on thyroid cancer." (PMID 36937508, 2023). "Several studies have reported greater expression of HIF-1α and HIF-2α in thyroid cancer compared to normal thyroid tissue or benign lesions, and a strong correlation has been observed between HIF-2α expression and tumor size." (PMID 36699028, 2022). "In thyroid cancer cells, NOX4 has been shown to stabilize HIF1α in hypoxic conditions by increasing mitochondrial ROS, enabling cell proliferation." (PMID 35682803, 2022). "Studies have shown that in all types of thyroid cancers, especially in FTC and ATC, the levels of HIF-1α were significantly higher than those in normal tissue." (PMID 33996538, 2021). "Among thyroid cancer cell lines, BCPAP cells expressed HIF-1α in both normoxic and hypoxic conditions." (PMID 32847004, 2020). "Another target for HIF-1α is the MET oncogene, which is overexpressed in thyroid cancers, especially medullary thyroid cancer (MTC), thereby promoting angiogenesis, cellular motility, invasion, and metastasis." (PMID 31533238, 2019). "Our in vitro studies also demonstrated a dose-dependent decrease in the expression of HIF-1α and GLUT1 in thyroid cancer cells after vitamin C treatment." (PMID 29084538, 2017).
thyroid cancer (continued). "Expression of HIF-1α and HIF-2α as well as vitamin C content was analyzed in thyroid lesions and cultured thyroid carcinoma cell lines (FTC-133 and 8305c) treated with hypoxia-mimetic agent (cobalt chloride) and ascorbic acid." (PMID 29084538, 2017). "As a result, HIF1A overexpression in OSAS may accelerate the occurrence and progression of thyroid cancer." (PMID 36937508, 2023). "The protein expression of HIF-1αwas significantly affected by KDM1A in thyroid cancer cells, but the mRNA level of HIF-1α was not regulated by KDM1A." (PMID 35198054, 2022). "There is no trace of HIF-1α expression in normal thyroid tissue but on the other hand in the most aggressive dedifferentiated thyroid cancers its expression is high." (PMID 32493394, 2020). "Our findings suggest that promoting the degradation of HIF-1α could be a strategy to manage progression and that HIF-1α inhibitors are potent drugs for thyroid cancer treatment." (PMID 32847004, 2020). "HIF1α is not expressed in healthy tissues, but it is expressed in thyroid cancer, especially in more aggressive forms like ATC." (PMID 31109060, 2019). "HIF-1α can activate the downstream factor VEGF, and its expression correlates with tumor progression in various carcinomas, such as pancreatic cancer, cervical carcinoma, and thyroid cancer." (PMID 27936049, 2016). "Moreover, there have been several studies which respectively showed that HIF-1α and HIF-2α are both upregulated in thyroid carcinoma compared with normal thyroid or benign lesion." (PMID 26846782, 2016). "To further identify the effect of our SRC kinase inhibitor on thyroid cancer cell lines, we examined the activation of HIF-1α by ROS with or without SRC inhibition." (PMID 25149476, 2015). "In the current study we identify S1P as a non-hypoxic inducer of HIF-1α expression in thyroid cancer cells." (PMID 23824493, 2013). "In conclusion we identify S1P, a bioactive lipid readily available in blood, as a non-hypoxic regulator of HIF-1α expression in thyroid cancer cells." (PMID 23824493, 2013). "In the present study we identify S1P as a non-hypoxic inducer of HIF-1α expression in thyroid cancer cells." (PMID 23824493, 2013). "In thyroid cancer cell lines, overexpression of BHLHE41 downregulated HIF-1α protein and mRNA levels and obviously repressed cell migration and invasion, revealing that BHLHE41 may play a tumor suppressor effect in thyroid cancer by modulating the HIF-1α pathway." (PMID 35615737, 2022). "Furthermore, because an EMT phenotype is generally observed at the invasive fronts of thyroid cancer tissues, while HIF-1α is usually expressed in cells in hypoxic, central regions of cancers, the significance of HIFα-induction of EMT in thyroid cancers is unclear." (PMID 26973599, 2016). "Moreover, it is known that HIF1α activity is also induced in non-hypoxic conditions by the hyperactivation of PI3K and RAS/RAF/ERK pathways, which is a direct consequence of genetic alterations that are common in thyroid cancer, such as PTEN deletion and RAS and BRAF mutations." (PMID 33916320, 2021). "Notably, HIF-1α was detected even without hypoxic stimuli, which implies that the BCPAP cell line is a good model for research of thyroid cancer where HIF-1α is highly expressed." (PMID 32847004, 2020). "Strikingly, we found that HIF1α rescued the decreased proliferation of NOX4 knockdown cells, but not restoring the mROS levels, reflecting that NOX4 regulates thyroid cancer cell growth dependent on mROS-HIF axis, rather than HIF-mROS." (PMID 30367082, 2018).
head and neck squamous cell carcinoma (57 papers, 2009 to 2025). A squamous cell carcinoma that arises from any of the following anatomic sites: lip and oral cavity, nasal cavity, paranasal sinuses, pharynx, larynx, and salivary glands. "Beasley and colleagues reported that expression of HIF1α in surgically treated patients with head and neck squamous cell carcinoma was associated with improved disease-free survival and overall survival." (PMID 21812995, 2011). "The adenosine A2A receptor (A2AR) has been associated with advanced pathological grade along with HIF-1α expression in head and neck squamous cell carcinoma (HNSCC)." (PMID 33348579, 2020). "Slug is extremely elevated in head and neck squamous cell carcinoma (HNSCC) cells in response to hypoxia/HIF-1α overexpression, which is also associated with a cadherin switch, the risk of lymph node metastasis, and a more advanced TNM stage." (PMID 32059478, 2020). "Previous studies have shown that HIF-1α upregulation following NRCHT is associated with tumor cell proliferation, stemness and reduced immune response in esophageal and head and neck squamous cell carcinomas." (PMID 35993091, 2022). "HOXA9 as an oncogene upregulated in Head and neck squamous cell carcinoma (HNSCC) is also reported to be related with HIF-1a signaling pathway." (PMID 36376832, 2022). "HIF-1α mainly describes the radioresistance of CSCs of head and neck squamous cell carcinoma to both photon and carbon ion irradiation, which makes the HIF-1α targeting an attractive therapeutic challenge." (PMID 36014432, 2022). "Downregulation of the expression of HIF‐1α led to an increase in the sensitivity of head and neck squamous cell carcinoma to the OSI-906 IGF1R small molecule inhibitor by a mechanism involving the increase in apoptosis." (PMID 35307810, 2022). "Supporting this, in head and neck squamous cell carcinomas, HIF-1α and HIF-2α expressions positively correlate with a higher rate of local failure after chemoradiotherapy treatment." (PMID 34539584, 2021). "Silencing HIF-1α under hypoxia leads to substantial radiosensitization of Head-and-Neck Squamous Cell Carcinoma (HNSCC) cells after both photons and C-ions." (PMID 34359734, 2021). "MPT0B098 significantly inhibited HIF-1α expression, epithelial-to-mesenchymal morphology changes, and migratory ability in the human head and neck squamous cell carcinoma cell line OEC-M1." (PMID 29592811, 2018). "Cetuximab, an anti-EGFR antibody used for cancer therapy, was reported to be able to sensitize human head and neck squamous cell carcinoma cells to radiation in part through inhibiting radiation-induced upregulation of HIF-1α." (PMID 25997612, 2015). "In present study, we did observe a positive association between HIF-1α expression and CD34 Chalkey count of primary tumor vascularity similar to a report for head and neck squamous cell carcinoma patients." (PMID 24165149, 2013). "Therefore, it is of interest to evaluate the expression of HIF-1α andHIF-2α proteins to correlate with clinical outcomes in patients with head and neck squamous cell carcinoma (HNSCC)." (PMID 40636217, 2025). "Moreover, GRIM-19 inhibits the aerobic glycolysis, cell proliferation, and tumorigenesis of head and neck squamous cell carcinoma by inhibiting HIF-1α/STAT3." (PMID 37118800, 2023). "Another study found that cetuximab inhibited glycolysis in cetuximab-sensitive head and neck squamous cell carcinoma (HNSCC) cells by down-regulating the expression of HIF-1α and suppressing the expression of the downstream target gene lactate dehydrogenase A (LDH-A)." (PMID 36139386, 2022). "However, silencing HIF1-α under hypoxia induced a radiosensitization of HNSCC (Head-and-Neck Squamous Cell Carcinoma) cell lines and their CSC subpopulation either with photons or C-ions." (PMID 34359734, 2021).
head and neck squamous cell carcinoma (continued). "Initial prospective and dynamic data could thereby show an association of HIF1a expression and an increased (18F)-FMISO tumor uptake, indicating hypoxic conditions in a cohort of head and neck squamous cell carcinoma (HNSCC)." (PMID 32984043, 2020). "In pre-clinical studies of head and neck squamous cell carcinoma cells that express HIF1α, it was found that in the setting of hypoxia, where HIF1α expression is increased, the cytotoxicity of SN38, the active metabolite of irinotecan, was enhanced with the addition of MSA." (PMID 30513765, 2018). "Indeed, HIF1α has been identified as a poor prognostic factor in patients with head and neck squamous cell carcinoma treated with radiotherapy." (PMID 28881665, 2017). "Our previous work demonstrated that small molecule EGFR inhibitors including erlotinib decreased VEGF mRNA expression, decreased secretion of VEGF protein, and blunted HIF-1α induction in response to hypoxia in SQ20B head and neck squamous cell carcinoma cells." (PMID 19657384, 2009). "In head and neck squamous cell carcinoma (HNSCC), GATA3 associates with HIF1α under hypoxia to inhibit the ubiquitination and proteasomal degradation of HIF1α, a mechanism independent of HIF1α prolyl-4-hydroxylation." (PMID 39942749, 2025). "It is known that hypoxic tumor cells, such as human head and neck squamous cell carcinoma (HNSCC), overexpress the HIF-1α." (PMID 34205571, 2021). "For example, an epidermal growth factor receptor (EGFR) inhibitor, cetuximab, which is approved by the FDA, suppresses the expression of HIF-1α and sensitizes head and neck squamous cell carcinoma (HNSCC) cells to radiotherapy." (PMID 34200019, 2021). "In clinical samples, GATA3 expression positively correlates with HIF-1α and is an independent predictor for poor disease-free survival in head and neck squamous cell carcinoma (HNSCC)." (PMID 28263977, 2017). "Snail is identified as a HIF-1α target gene in mouse; Twist is directly regulated by HIF-1α in head and neck squamous cell carcinoma (HNSCC)." (PMID 26057751, 2015). "Leeman-Neill and colleagues also reported that Guggulsterone inhibited STAT3 and HIF-1α and suggested a biologic rationale for further clinical investigation BA for human head and neck squamous cell carcinoma (HNSCC) therapy." (PMID 21731766, 2011). "For instance, in head and neck squamous cell carcinoma (HNSCC), hypoxia-inducible factor 1α (HIF-1α) binds to the MFF and upregulates its expression." (PMID 41573644, 2025). "For example, targeting EGFR with erlotinib (Tarceva, Genentech) induces vascular normalization by reducing the expression of hypoxia-inducible factor-1α (HIF-1α) and VEGF in head and neck squamous cell carcinoma (HNSCC) xenograft models." (PMID 37907742, 2023). "The relationships between GLUT1, HIF1α expression and 18F-FDG uptake in head and neck squamous cell carcinoma(HNSCC) remain controversial." (PMID 28410229, 2017). "Specifically in head and neck squamous cell carcinoma TKTL1 is activated by promoter hypomethylation and drives carcinogenesis by increased aerobic glycolysis and hypoxia inducible factor 1 alpha (HIF-1α) stabilization." (PMID 24304513, 2013). "Furthermore, in head and neck squamous cell carcinoma, with inhibition of STAT3 activation, HIF-1α expression is repressed." (PMID 33681184, 2020). "Although miR-31 modulated the expression of FIH1 in NPC cells, it did not alter HIF1α expression as shown in head and neck squamous cell carcinoma (HNSCC)." (PMID 25098679, 2014). "The hypoxic microenvironment in primary head and neck squamous cell carcinomas (HNSCC) and breast tumors induces the selection of a fraction of cells that concomitantly express hypoxia-related genes (GLUT1 and HIF-1α) and long-term dormancy genes, such as NR2F1, DEC2, and p27." (PMID 35158815, 2022).
head and neck squamous cell carcinoma (continued). "In addition, co-expression of TWIST1, HIF-1α and SNAIL has been correlated with metastasis and poor prognosis in primary tumors of head and neck squamous cell carcinoma (HNSCC) patients." (PMID 23741524, 2013).